SUSD4 (sushi domain containing 4)
Description:
Acts as a complement inhibitor by disrupting the formation of the classical C3 convertase. Isoform 3 inhibits the classical complement pathway, while membrane-bound isoform 1 inhibits deposition of C3b via both the classical and alternative complement pathways.
Synonyms: FLJ10052; PRO222
Tractability: Antibody: UniProt places it where antibodies can reach, with high confidence; UniProt predicts a signal peptide or a membrane-spanning region; its Gene Ontology location is reachable by antibodies, with medium confidence.
Gene: Protein-coding gene on chromosome 1 (223,220,819 to 223,365,279, reverse strand). Ensembl gene ENSG00000143502.
Subcellular location: Membrane (Isoform 1); Secreted (Isoform 3)
Subcellular location (Human Protein Atlas): Vesicles
Gene Ontology:
Biological process: regulation of complement activation; regulation of postsynaptic neurotransmitter receptor internalization
Cellular component: extracellular region; membrane; parallel fiber to Purkinje cell synapse; postsynaptic membrane
Genetic constraint (gnomAD): Loss-of-function variants: 41 observed, 51.36 expected, observed/expected ratio (o/e) 0.8, 90% interval 0.62 to 1.04. The upper end of that interval is the gene's LOEUF score, 1.04, which puts it in group 4 of 6, group 1 being the genes least tolerant of losing a copy. Missense variants: 580 observed, 655.33 expected, observed/expected ratio (o/e) 0.89, 90% interval 0.83 to 0.95. Synonymous variants: 257 observed, 265.59 expected, observed/expected ratio (o/e) 0.97, 90% interval 0.87 to 1.07.
Homologues: Orthologues: chimpanzee SUSD4 (99% identical), macaque SUSD4 (96% identical), rat Susd4 (92% identical), mouse Susd4 (91% identical), rabbit SUSD4 (91% identical), pig SUSD4 (74% identical), dog SUSD4 (67% identical), tropical clawed frog susd4 (57% identical), zebrafish susd4 (51% identical). Paralogues in human: CSMD3 (22% identical), CSMD2 (21% identical), CSMD1 (21% identical), SVEP1 (18% identical), CR1 (18% identical), SEZ6L (18% identical), SEZ6 (17% identical), CFH (17% identical), SEZ6L2 (17% identical), CR2 (16% identical), SELP (15% identical), C4BPA (14% identical), and 27 more.
Diseases named in the same sentence as SUSD4 in open-access papers:
SUSD4 is named in the same sentence as 21 diseases in open-access papers, as found by Europe PMC text mining. Sharing a sentence is not in itself a finding about the gene and the disease. The quoted sentences say what the papers report.
breast carcinoma (3 papers, 2015 to 2024). "As SUSD4 is a poorly described protein, a broad screen of proteins differentially expressed in the presence of SUSD4 was employed to identify its underlying tumor-suppressive mechanism in breast cancer." (PMID 36578014, 2022). "Our findings indicate that SUSD4 expression in both breast cancer cells and T cells infiltrating the tumor-associated stroma is useful to predict better prognosis of breast cancer patients." (PMID 26480818, 2015). "SUSD4 expression also inhibited colony formation of human breast cancer cells cultured on carcinoma-associated fibroblasts." (PMID 26480818, 2015). "In this study, we showed that SUSD4 expression in tumor cells and tumor-infiltrating cells was associated with higher survival rates of breast cancer patients." (PMID 26480818, 2015). "Here, we show that breast cancer epithelial cells express SUSD4 and that positive expression was significantly associated with a prolonged patient survival." (PMID 26480818, 2015). "Furthermore, large numbers of SUSD4-expressing T cells in the tumor stroma associated with better overall survival of the breast cancer patients." (PMID 26480818, 2015). "Furthermore, expression of SUSD4 is associated with an improved prognosis for breast cancer patients." (PMID 26480818, 2015). "Existing research has predominantly centered on assessing SUSD4 expression levels in lung adenocarcinoma and breast cancer contexts." (PMID 38579174, 2024). "The expression of SUSD4 was previously correlated with a better prognosis for breast cancer patients." (PMID 36578014, 2022). "In general, breast cancer cell lines were very hard to transfect in a stable manner with SUSD4 and some rapidly lost their expression in culture." (PMID 36578014, 2022). "Here we provide further evidence corroborating a tumor suppressive role of SUSD4 as well as novel mechanistic insight into the role of SUSD4 in breast cancer cells, revealing both interaction partners and an autophagy-promoting effect." (PMID 36578014, 2022). "Expression of SUSD4 in the breast cancer cells led to activation of the tumor suppressor LKB1 and consequently to the activation of AMPKα1." (PMID 36578014, 2022). "The same phenomenon was also observed for the triple negative mouse breast cancer cell line 4 T1-Luc2 stably expressing mouse SUSD4-FLAG, which had been treated with chloroquine for 3 hours." (PMID 36578014, 2022). "In a syngeneic mouse model of breast cancer, tumors expressing SUSD4 had a smaller volume compared with the corresponding mock control tumors." (PMID 36578014, 2022). "We previously demonstrated that the expression of SUSD4 by tumor cells was correlated with a better prognosis for breast cancer patients." (PMID 36578014, 2022). "Unpredictably, we also found that breast cancer patients with SUSD4 expressing tumors had improved overall survival and less recurrence compared to those with non-expressing tumors." (PMID 36578014, 2022). "Further studies are needed to fully elucidate the roles of the novel breast cancer suppressor SUSD4 in both cancerous cells as well as in the brain, where it is highly expressed." (PMID 36578014, 2022). "Onwards, using single cell RNA sequencing data obtained from the Broad Institute Single Cell Portal, enabled for the expression of SUSD4 in both epithelial cells of various breast cancer subtypes and in different stromal cells to be evaluated." (PMID 36578014, 2022). "Looking at the expression of SUSD4 in various subtypes of breast cancer revealed an upregulation in the subtypes luminal A and luminal B, which have a better prognosis." (PMID 36578014, 2022). "The effect of SUSD4 expression on cell migration and invasion was studied in vitro using two human breast cancer cell lines overexpressing SUSD4." (PMID 26480818, 2015). "RNA was purified from breast cancer tissues isolated from patients included in a second independent cohort, and SUSD4 transcript levels were analysed by qPCR." (PMID 26480818, 2015).
breast carcinoma (continued). "Using immunohistochemistry and quantitative PCR, we investigated SUSD4 expression in breast cancer tissue samples from two cohorts." (PMID 26480818, 2015). "In summary, SUSD4 expression by tumor cells improved the survival rate of breast cancer patients and led to decreased growth rate and migration of transfected cells in vitro." (PMID 26480818, 2015). "In order to determine which type of stromal infiltrating cells expressed SUSD4, fluorescent double-stainings were performed on the human breast cancer sections." (PMID 26480818, 2015). "Additionally, SUSD4 was found to be downregulated in HER2 enriched breast cancer and unchanged in Normal-like breast cancer." (PMID 36578014, 2022). "Additionally, data from three different expression databases and online analysis tools confirm that for breast cancer patients, high mRNA expression of SUSD4 in the tumor tissue correlates with a better prognosis." (PMID 36578014, 2022). "The same online tool used for a Kaplan-Meier survival analysis of mRNA sequencing data of breast cancer patients in the pan-cancer project (n = 936), further corroborated a longer relapse free survival correlated with high expression of SUSD4 (Log-rank p = 0.034)." (PMID 36578014, 2022). "Moreover, forced SUSD4 expression in human breast cancer cells attenuated their migratory and invasive traits in culture." (PMID 26480818, 2015). "In this study, we aimed to identify the role of SUSD4 in breast cancer." (PMID 26480818, 2015). "In our previous study, we detected SUSD4 positive tumor-infiltrating cells in colon, lung and breast cancer, suggesting that SUSD4 might play a role in cancer progression." (PMID 26480818, 2015). "Kaplan-Meier analyses and Breslow tests showed that SUSD4 expression in tumor cells and in the tumor infiltrating cells had a positive effect on the breast cancer specific survival rate of the patients, but did not significantly affect recurrence free survival." (PMID 26480818, 2015). "Therefore we now aimed to assess the expression of the complement inhibitor SUSD4 in human breast cancer and to determine if the degree of expression may be related to clinical prognosis." (PMID 26480818, 2015). "We obtained the expression matrix of SUSD4 in various cancer cell lines through the CCLE database and found that the expression level of SUSD4 was highest in breast cancer, while it was lowest in lymphoma, rhabdoid, and myeloma." (PMID 38579174, 2024). "To gain more insight into the connection between SUSD4 and EGFR we assessed their expression in individual cell types present in breast cancer using data from the Broad Institute Single Cell Portal." (PMID 36578014, 2022). "We also propose a potential role for SUSD4 in EGFR trafficking and recycling in breast cancer cells." (PMID 36578014, 2022). "Data now obtained from the Gene expression-based Outcome for Breast cancer Online (GOBO) database and assessed by Kaplan-Meier survival analysis further corroborated a positive outcome related to SUSD4 expression." (PMID 36578014, 2022). "Although it is known that the presence of infiltrating T cells is beneficial for breast cancer-specific survival, it has not been shown that these cells express SUSD4, which is here identified as a protein suppressing the aggressive phenotype of breast cancer cells." (PMID 26480818, 2015).
Cirrhosis (1 paper, 2014). A chronic disorder of the liver in which liver tissue becomes scarred and is partially replaced by regenerative nodules and fibrotic tissue resulting in loss of liver function. "Interestingly, we observed that a subset of these DMRs arise during cirrhosis and are enhanced in the magnitude of methylation change in HCC, exemplified by the HOXA and SUSD4 loci." (PMID 25294808, 2014).
colorectal adenocarcinoma (1 paper, 2024). The most common type of colorectal carcinoma. "Conversely, in colorectal adenocarcinoma, liver hepatocellular carcinoma, and kidney renal papillary cell carcinoma, high SUSD4 expression was significantly associated with poor prognosis and increased immune cell infiltration." (PMID 38579174, 2024). "Moreover, our exploration uncovered a distinctive association between SUSD4 and colorectal adenocarcinoma, prompting us to delve deeper into this connection from multiple perspectives." (PMID 38579174, 2024).
colorectal cancer (1 paper, 2024). A primary or metastatic malignant neoplasm that affects the colon or rectum. "Consequently, we performed gene set enrichment analysis (GSEA) in COADREAD to unravel the potential mechanisms underlying the oncogenic actions of SUSD4 in colorectal cancer." (PMID 38579174, 2024). "These insights offer a more comprehensive understanding of SUSD4’s function in cancer biology, specifically in colorectal cancer, and highlight its interaction with the JAK/STAT signaling pathway." (PMID 38579174, 2024). "To investigate the potential oncogenic role of SUSD4, we conducted knockdown experiments in colorectal cancer cell lines." (PMID 38579174, 2024). "In-depth investigation in colorectal cancer uncovers SUSD4’s role in cell proliferation via the JAK/STAT signaling pathway and its potential as a therapeutic marker." (PMID 38579174, 2024). "Firstly, we verified the expression of SUSD4 in various colorectal cancer cell lines and found the highest expression in DLD1 and LOVO." (PMID 38579174, 2024). "Additionally, leveraging the single-sample gene set enrichment analysis (ssGSEA) algorithm, we corroborated the correlation between SUSD4 expression levels and prevalent cancer-related pathways in colorectal cancer." (PMID 38579174, 2024). "Additionally, we validated the function of SUSD4 in colorectal cancer cell lines and found that knockdown of SUSD4 inhibited cell growth and impacted the JAK/STAT pathway." (PMID 38579174, 2024). "Comprehending the intricate interplay among SUSD4, JAK/STAT signaling, and colorectal cancer prognosis offers potential for identifying novel therapeutic targets and devising personalized treatment strategies for patients." (PMID 38579174, 2024).
dementia (1 paper, 2025). Loss of intellectual abilities interfering with an individual's social and occupational functions. "For male-specific relationships, SUSD4-inflammatory bowel disease (Inverse variance weighted (IVW) fixed effects meta-analysis MR estimate q-value in males = 0.038, in females = 1.00) and NCAM1-dementia (q-value in males = 0.045, q-value in females = 1.00) pairs were identified." (PMID 40877285, 2025).
triple-negative breast carcinoma (1 paper, 2022). An invasive breast carcinoma which is negative for expression of estrogen receptor (ER), progesterone receptor (PR), and human epidermal growth factor receptor 2 (HER2). "The triple negative breast cancer cell line BT-20 was stably transfected with a vector encoding human SUSD4 or a mock control vector." (PMID 36578014, 2022). "In vitro, triple negative breast cancer cell lines expressing SUSD4 migrated slower and invaded through Matrigel with lower efficacy." (PMID 36578014, 2022). "Furthermore, triple-negative breast cancer cell lines stably expressing SUSD4 had higher autophagic flux." (PMID 36578014, 2022). "In this study, SUSD4 was found to interact with the tyrosine-kinase receptors EGFR and PDGFRα in triple negative breast cancer cell lines." (PMID 36578014, 2022). "In vitro experiments utilized triple-negative breast cancer cell lines (BT-20 and MDA-MB-468) stably expressing SUSD4." (PMID 36578014, 2022).
cancer (5 papers, 2014 to 2024). A tumor composed of atypical neoplastic, often pleomorphic cells that invade other tissues. "Continued exploration of the functional roles and molecular mechanisms linked with SUSD4 is imperative to attain a profound comprehension of its relevance in cancer biology." (PMID 38579174, 2024). "Results showed that the expression level of SUSD4 was associated with prognosis, immunity, and heterogeneity in some types of cancer, and we attempted to utilize enrichment analysis to predict the possible mechanism of SUSD4." (PMID 38579174, 2024). "Significantly, the regulatory correlations associated with SUSD4 were found to be dependent on the specific cancer type." (PMID 38579174, 2024). "According to the results, there is an association between the expression level of SUSD4 and prognosis in multiple types of cancer." (PMID 38579174, 2024). "In addition, SUSD4 expression level was negatively associated with cancer proliferation, DNA repair, cellular response to hypoxia, DNA replication, MYC target genes, and G2M DNA damage checkpoint." (PMID 38579174, 2024). "Considering that CNAs may be associated with cancer progression, we investigated the association between SUSD4 expression level and CNV." (PMID 38579174, 2024). "Overall, a prevailing trend emerged wherein the correlation between SUSD4 expression and immune-related genes tended to be positive across various cancer types." (PMID 38579174, 2024). "The results revealed a relatively high overall frequency of SUSD4 alterations in various types of cancer, primarily driven by copy number variations (CNVs)." (PMID 38579174, 2024). "The study underscores the significance of SUSD4 in cancer biology, suggesting it as a promising therapeutic target and prognostic indicator across diverse cancer types, while acknowledging the need for further mechanistic exploration and validation." (PMID 38579174, 2024). "Through this systematic approach, we aim to unveil novel perspectives on the potential relevance of SUSD4 in the landscape of cancer research." (PMID 38579174, 2024). "Nevertheless, the exploration of SUSD4’s involvement in tumor immunity and prognostic implications across various cancer types remains limited in prior research efforts." (PMID 38579174, 2024). "In conclusion, SUSD4 is a valuable prognostic indicator for diverse types of cancer, and it has the potential to be a target for cancer therapy." (PMID 38579174, 2024). "To date, scant attention has been devoted to the exploration of Sushi domain-containing protein 4 (SUSD4), with a paucity of studies investigating its implications across diverse cancer types." (PMID 38579174, 2024). "Further analysis demonstrated that SUSD4 expression level was related to immune cell infiltration, immune-related genes, tumor heterogeneity, and multiple cancer pathways." (PMID 38579174, 2024). "Through correlation analysis between SUSD4 expression and immune-related genes, we found a general positive correlation between SUSD4 and immune-related genes in cancers where high expression of SUSD4 is a poor prognostic factor." (PMID 38579174, 2024). "Further investigation into these mechanisms holds promise for enhancing our understanding of the role of SUSD4 in cancer progression, as well as for guiding the development of targeted therapeutic strategies." (PMID 38579174, 2024). "Adopting a systematic pan-cancer approach, the present investigation aims to elucidate the multifaceted dynamics of SUSD4 expression levels vis-à-vis cancer prognosis." (PMID 38579174, 2024). "Our analysis demonstrated a positive correlation between CNV and SUSD4 expression level across diverse types of cancer." (PMID 38579174, 2024). "Our analysis of SUSD4 genetic alterations in pan-cancer datasets from TCGA was conducted using the cBioPortal." (PMID 38579174, 2024). "Among the immunoinhibitory genes, VTCN1 expression level was positively correlated with SUSD4 expression level in many types of cancer." (PMID 38579174, 2024).